EGF (epidermal growth factor)
Diseases named in the same sentence as EGF in open-access papers (continued):
Sharing a sentence is not in itself a finding about the gene and the disease.
non-small cell lung carcinoma (108 papers, 1992 to 2025). A group of at least three distinct histological types of lung cancer, including non-small cell squamous cell carcinoma, adenocarcinoma, and large cell carcinoma. "Oncogenic mutations in EGFR often result in EGF-independent constitutive activation and aberrant trafficking and are associated with several human malignancies, including non-small cell lung cancer." (PMID 40259053, 2025). "Randomized phase three trial on patients with epidermal growth factor (EGFR) mutation stage II-IIIA non-small cell lung cancer (NSCLC) gave adjuvant Gefitinib (G) treatment versus vinorelbine plus cisplatin (VP) to assess overall survival (OS)." (PMID 36788891, 2023). "Although epidermal growth factor (EGFR)-tyrosine kinase inhibitors (TKIs) have significantly improved the prognosis of advanced non-small cell lung cancer (NSCLC) patients with EGFR mutations, patients often develop resistance to these drugs." (PMID 35655775, 2022). "Patients with non-small cell lung cancer (NSCLC) with specific mutations in the tyrosine kinase domain of the epidermal growth factor (EGFR) gene have favorable clinical outcomes with EGFR tyrosine kinase inhibitor (EGFR-TKI) therapy." (PMID 28158206, 2017). "Activating mutations within the epidermal growth factor (EGFR) tyrosine kinase domain identify non-small cell lung cancer patients with improved clinical response to tyrosine kinase inhibitor therapy." (PMID 19174819, 2009). "We investigated this by extracting total intravesicular nucleic acid content from sEVs isolated from the conditioned cell medium of the human NCI-H1975 cell line containing the epidermal growth factor (EGFR) gene mutation T790M as a model system for non-small cell lung cancer." (PMID 36555692, 2022). "To date, therapeutic NCD vaccines that have been approved for clinical use include CimaVax-EGF (for non-small cell lung cancer), Sipuleucel-T (for prostate cancer), and Inclisiran (for dsylipidemia)." (PMID 40872964, 2025). "In non-small cell lung cancer, this invasive pathway occurs in the Nav1.7 subunit through the epidermal growth factor (EGF) - signal-regulated and kinase 1/2 (ERK1/2) pathway." (PMID 40223925, 2025). "Cimavax-EGF, an epidermal growth factor (EGF)-targeting vaccine approved in Cuba for non-small cell lung cancer (NSCLC), extended median survival from 6 months to >5 years in responders by neutralizing EGF and inhibiting tumor proliferation." (PMID 40507941, 2025). "Gefitinib (also known as Iressa or ZD1839) is an epidermal growth factor (EGFR) tyrosine kinase inhibitor (TKI) widely used to treat advanced non-small cell lung cancer (NSCLC)." (PMID 41425704, 2025). "The first orally active selective EGF inhibitor was approved by the FDA for advanced non-small cell lung cancer (NSCLC)." (PMID 40940907, 2025). "Epidermal growth factor (EGF) was reported to promote the migration and invasion of prostate and non-small cell lung cancer cells by increasing Nav1.7 expression." (PMID 39060933, 2024). "Gefitinib, erlotinib, and lapatinib are EGF inhibitors clinically approved by the FDA for the treatment of advanced non-small cell lung cancer (NSCLC); icotinib has been registered for such use in Asia." (PMID 39684570, 2024). "Further emphasizing targeted approaches, docetaxel and resveratrol were encapsulated in epidermal growth factor receptor-targeted lipid–polymer hybrid nanoparticles (EGF DTX/RSV LPNs) designed for the targeted treatment of non-small cell lung cancer (NSCLC)." (PMID 38794306, 2024). "Reducing circulating EGF with an EGF-based vaccine has been successfully used for the treatment of advanced non-small cell lung cancer patients, as switch maintenance." (PMID 39203959, 2024). "Antitumor effects of melittin were assessed in NSCLC (non-small cell lung cancer) cells and exhibited the inhibition of EGF-induced migration and invasion." (PMID 37513529, 2023).
non-small cell lung carcinoma (continued). "CIMAvax-EGF is an epidermal growth factor (EGF)-depleting immunotherapy which has shown survival benefit as a switch maintenance treatment after platinum-based chemotherapy in advanced non-small cell lung cancer (NSCLC)." (PMID 35992783, 2022). "In contrast, other studies found that THC inhibited epidermal growth factor (EGF) stimulated growth of non-small cell lung cancer and reduced the expression of EGFR, as well as chemotaxis and invasion." (PMID 32708138, 2020). "The study of non-small cell lung cancer shows that the ability of EGF to promote cell invasion deceases after silencing Nav1.7 expression, suggesting that EGF can enhance cell invasion by regulating VGSC." (PMID 30895169, 2019). "In prostate and non-small cell lung cancer cells, epidermal growth factor (EGF) can upregulate the expression of Nav1.7 and promote the migration of cancer cells or promote cell invasion through the ERK1 /2 pathway, respectively." (PMID 30895169, 2019). "Knockdown of NEDD4 significantly reduced EGF-stimulated cell migration in non-small cell lung carcinoma (NSCLC) cells." (PMID 29455656, 2018). "In the present study, we carefully examined the EGF-induced degradation of endogenous EGFR proteins in a panel of non-small cell lung cancer cell lines." (PMID 29976202, 2018). "Our previous studies have shown that in non-small cell lung cancer and cervical cancer cell lines, EGF stimulation can promote intracellular Rab35 activity, thereby promoting tumor cell migration or proliferation." (PMID 30524285, 2018). "A similar result was found by other authors in a phase III study of an EGF-based vaccine for the treatment of patients with non-small cell lung cancer." (PMID 30426104, 2018). "We investigated the migratory behavior of different collectively migrating non-small cell lung cancer cell lines in response to motogenic growth factors (e.g. epidermal growth factor) or clinically relevant small compound inhibitors." (PMID 28649432, 2017). "In non-small cell lung cancer, Nav17 is required for the epidermal growth factor (EGF)-mediated extracellular signal-regulated kinase 1/2 (ERK1/2) pathway to enhance cell invasion." (PMID 28264681, 2017). "CIMAvax-EGF demonstrated to be safe and immunogenic in advanced non-small cell lung cancer (NSCLC) patients." (PMID 28348561, 2017). "Previous study published that hyperimmune sera obtained in non-small cell lung cancer patients treated with an EGF-based vaccine was able to inhibit the HER1 phosphorylation trough the anti-EGF specific antibodies." (PMID 28539888, 2017). "Here, we used functional genomics to identify oncogenic miRNAs in non-small cell lung cancer and evaluate their impact on response to epidermal growth factor (EGFR)-targeting therapy." (PMID 27477696, 2017). "Other evidence of miR-193a association with PI3K/Akt has been shown in non-small-cell lung cancer, where it suppresses metastasis by targeting the receptor tyrosine-protein kinase ERBB4, a member of the epidermal growth factor (EGF) receptor subfamily, and inhibiting the downstream PI3K/Akt cascade." (PMID 40801567, 2025). "Similarly, CIMAvax-EGF, targeting the epidermal growth factor for non-small-cell lung cancer (NSCLC), merges recombinant EGF with a protein carrier." (PMID 37895855, 2023). "Targeted therapy against epidermal growth factor (EGFR) mutations has become the standard of care for non-small cell lung cancer, and there has not been an efficient genetic test for non-small cell lung cancer patients." (PMID 36230590, 2022). "In addition, TRPC1 was identified in human non-small cell lung carcinoma (NSCLC) cells as a major regulator for EGF signaling that affects cell proliferation." (PMID 36139480, 2022).
non-small cell lung carcinoma (continued). "Silencing NRF2 by RNA interference also inhibited tumor growth and increased efficacy of chemotherapy or EGF-driven proliferation in non-small cell lung cancer models and reduced the proliferation and drug-resistance in human lung cancer cells or human pancreatic cancer cells." (PMID 24366069, 2014). "For example, monoclonal antibodies that bind the EGFR extracellular domain can promote downregulation, and the endocytosis of EGFR induced by EGF is closely related to the sensitivity to the tyrosine kinase inhibitor gefitinib in non-small cell lung cancer cell lines." (PMID 23631593, 2013). "ISA 51 is used in a non-small-cell lung cancer vaccine, CimaVax EGF, in Cuba and Chile." (PMID 20808862, 2010). "CAR-T cells have been developed against EGFR (EGF-CAR-T) using the piggyBac system, and they showed a potent antitumor activity against non-small-cell lung cancer (NSCLC) cell lines in vitro and in vivo in NSG mice." (PMID 38727261, 2024). "Among RTKs, the family of receptors of Epidermal growth factor (EGF) has been extensively studied in various solid cancers, mainly in colorectal and non-small cell lung carcinomas." (PMID 37513953, 2023). "Interestingly, SHCBP1 also mediates EGF-induced activation of β-catenin signaling in non-small cell lung carcinoma (NSCLC) cells." (PMID 35013128, 2022). "In the non-small cell lung cancer (NSCLC) cell line A549, the TRPM7 channel is over-expressed after stimulation of epidermal growth factor (EGF), and an increased cell migration is observed." (PMID 36844925, 2022). "EGF was shown to induce the expression of CXC Chemokine Receptor 4 (CXCR4) and promote migration in normoxic non-small cell lung cancer (NSCLC) cells via HIF-1α and the PI3K/AKT and mTOR pathways." (PMID 35158804, 2022). "The addition of gefitinib, an EGFR-TKI used in clinical practice for diseases such as non-small cell lung cancer, significantly decreased the expression of CLDND1, which was increased by EGF." (PMID 35892692, 2022). "In non-small cell lung carcinoma cell line, the upregulation of VGSC induced by epidermal growth factor (EGF) promotes cell invasion." (PMID 35207698, 2022). "In another study, a bispecific immunotoxin, DTATEGF, targeting the EGF/EGFR and uPA/uPAR axes showed a potent cytotoxic effect in human metastatic non-small cell lung cancer (NSCLC) brain tumor xenografts." (PMID 33921923, 2021). "In contrast, in mouse embryonic fibroblasts, human embryonic kidney cells, and human A549 cells of non-small cell lung carcinoma, the fucosylation of EGFR is required for the binding of EGF and its subsequent signaling activity." (PMID 33238647, 2020). "EGF-induced nuclear translocation of β-catenin was also largely inhibited by depletion of PFKP in LN229 GBM cells and A549 non-small cell lung cancer cells." (PMID 32195176, 2020). "Significantly, PPI exhibited an inhibitory effect on epidermal growth factor (EGF) receptor tyrosine kinase inhibitors, which has a mutagenic and pro-EMT action in non-small cell lung cancer." (PMID 31417401, 2019). "The genes included the pathway non-small cell lung cancer were E2F2, E2F3, TGFA, PRKCG, CDK6, EGF, and CDK4, which were all expressed at significantly higher levels in LUSC tissues in comparison to that in the non-cancer group." (PMID 29394946, 2018). "In non-small-cell lung cancer (NSCLC), treatment with EGF or aberrant EGFR activation was shown to elevate NRF2 and its target gene expressions." (PMID 29291022, 2017). "We herein applied epidermal growth factor (EGF) and five EGF receptor (EGFR)-related kinase inhibitors to investigate the role of EGFR signaling in KPNA2 expression in non-small cell lung cancer (NSCLC) cells." (PMID 27009856, 2016). "The aim of the present study was to investigate the effect of DAPT, a γ-secretase inhibitor, in non-small cell lung cancer (NSCLC) cells, as well as the impact of epidermal growth factor (EGF) that is over-expressed by NSCLC cells, on Notch signaling." (PMID 26497899, 2015).
non-small cell lung carcinoma (continued). "With this device, we investigated the effects of epidermal growth factor (EGF) and matrix metalloproteinase (MMP) inhibitor, GM6001 on invadopodia formation by human non-small cell lung cancer cell line A549 in 3D matrix model." (PMID 23441195, 2013). "As an immunotherapy targeting epidermal growth factor (EGF), several clinical trials have been carried out in patients with advanced non-small-cell lung cancer (NSCLC), and the Cuban regulatory agency has approved CIMAvax-EGF as maintenance therapy after first-line treatment." (PMID 39766327, 2024). "Indeed, integrins potentiate the EGF-dependent EGFR activation in various cells, including human foreskin fibroblasts, ECV304 endothelial cells, A549 non-small cell lung cancer cells, and the SK-MES1 lung squamous carcinoma cells." (PMID 39594667, 2024). "Similarly, STMN3, a microtubule destabilizing protein, is induced by both nicotine and EGF in an ID1 dependent fashion, as well as can facilitate the proliferation, invasion and migration of non-small cell lung cancer." (PMID 37965307, 2023). "Nazartinib (EGF 816; NAZ) is a new anti-cancer candidate proposed as a third-generation epidermal growth factor receptor tyrosine kinase inhibitor that is being developed and clinically tested for the management of non-small cell lung cancer." (PMID 32218978, 2020). "Moreover, matrine restrains angiogenesis by reducing the expression of VEGF, EGF, VEGFR1, MMP-9, and MMP-2 in human non-small cell lung cancer (NSCLC) A549 cells and MDA-MB-231 cells." (PMID 31601793, 2019). "Similarly, plating of A549 non-small cell lung cancer cells on an anti-β1 integrin activating antibodies results in EGFR phosphorylation even in the absence of EGF." (PMID 39594667, 2024). "However, unlike non-small cell lung cancer (NSCLC), where useful markers such as EGFR gene mutation have already been established, the molecular markers regulating sensitivity to EGF/EGFR as well as those targeting VEGF/VEGFR in ESCC are hardly known." (PMID 24945674, 2014). "In non-small cell lung carcinoma (NSCLC), Tid1-S, but not Tid1-L, is required for the EGF-stimulated EGFR transportation into mitochondria, potentially leading to enhanced cancer cell migration and invasion." (PMID 34948322, 2021).
melanoma (105 papers, 2006 to 2026). A malignant, usually aggressive tumor composed of atypical, neoplastic melanocytes. "The loss of LRIG1 in A375 melanoma cells resulted in decreased expression of ERBB receptors upon EGF stimulation and decreased activation of ERBB3." (PMID 33786987, 2021). "It has been shown that the +61G/A substitution led to a decreased EGF production in vitro and decreased risk of malignant melanoma." (PMID 22829952, 2012). "Distribution of EGF genotypes and allele frequencies in Italy among melanoma and non-melanoma subjects." (PMID 19624835, 2009). "In a previous case-control study conducted in the United Kingdom, the 61A>G transversion (rs4444903) in the EGF gene has been correlated with an increased risk of melanoma in vivo." (PMID 19624835, 2009). "A single nucleotide polymorphism (61A>G) in the epidermal growth factor (EGF) gene has been implicated in both melanoma pathogenesis and increased melanoma risk." (PMID 19624835, 2009). "Mutations at this locus reduce EGF levels and increase the risk of malignant melanoma." (PMID 40696566, 2025). "Overexpression of Swiprosin-1 increased lamellipodia formation in B16F10 melanoma cells, whereas knockdown of Swiprosin-1 inhibited EGF-induced lamellipodia formation, and led to a loss of actin stress fibers at the leading edges of cells but not in the cell cortex." (PMID 23959172, 2013). "Our findings further suggest that EGF +61A>G polymorphism may have a limited impact on predisposition and/or pathogenesis of melanoma and its prevalence may vary in different populations." (PMID 19624835, 2009). "The EGF +61A>G polymorphism seems to play a limited role on either predisposition or pathogenesis of melanoma; prevalence of such a genetic variant may deeply vary in different populations." (PMID 19624835, 2009). "To investigate the role of phosphorylation and the actin cytoskeletal localization of FilGAP, we used A7 melanoma cells, which spread well on extracellular matrix, respond well to EGF and form lamellipodia." (PMID 38426123, 2024). "In conjunction with overexpression of EGFR, metastatic melanoma cells are demonstrated to overproduce the epidermal growth factor (EGF) ligand." (PMID 37181747, 2023). "Subsequently, melanoma cells were treated with EGF or Colivelin to further elucidate the regulatory effect of KIF22 on EGFR/STAT3 signaling." (PMID 37944197, 2023). "EGF can subsequently act in an autocrine signalling manner allowing melanoma cells to produce their own growth and survival signals, as well as in a paracrine manner acting on endothelial cells to drive neoangiogenesis." (PMID 37181747, 2023). "EGF can specifically bind to the EGF receptor overexpressed in many cancer cells such as melanoma cells, which can be used in targeted drug delivery." (PMID 35547773, 2022). "The anticancer activity against human melanoma cells and the prevention of the EGF-, TPA-, X-ray-, and UVB-induced neoplastic cell transformation of JB6 Cl41 cells of triterpene glycosides were investigated for the first time." (PMID 35323516, 2022). "In contrast, lower concentrations of BDNF, SDF-1α, MCP-1, Eotaxin, EGF, and IL-7 were observed in the serum of melanoma patients compared to healthy controls." (PMID 33574842, 2021). "In line with our observations, the inhibition of SRPK1 by SRPIN340 or trifluoromethyl arylamides maintained SRPK1 predominantly in the cytoplasm when melanoma cells were stimulated with EGF." (PMID 33808326, 2021). "In summary, NRF2 enhances EGFR activity by inducing the expression of EGFR and its ligands in melanoma, with EGF transcription being directly regulated by NRF2." (PMID 33916908, 2021). "In human melanoma cells, EGF treatment can promote STAT5 activation via tyrosine-protein kinase Src (Src) and Janus kinase 1 (JAK1) signaling leading to STAT5 nuclear translocation along with upregulation of the STAT5 target, Bcl-2, an antiapoptosis protein." (PMID 34067095, 2021).